MSH6 (mutS homolog 6)
Diseases named in the same sentence as MSH6 in open-access papers (continued):
Sharing a sentence is not in itself a finding about the gene and the disease.
cancer (continued). "The most frequent genes in patients with cancer were DNA polymerase theta (POLQ; n = 6) and MSH6 (n = 4) in women and POLQ (n = 4) in men." (PMID 36896836, 2023). "The increase in cancer incidence was MLH1: 7.76% vs. 3.84% and MSH6: 7.24% vs. 4.52%, and the increased cancer mortality was MLH1: 5.74% vs. 2.55% and MSH6: 5.22% vs. 2.97%." (PMID 36551605, 2022). "We also noted seven genes marked with “caution” in PeCanPIE showing the truncation close to the C-terminal (CUX1, FLCN, FLG, MSH6, NSD1, PRDM9, and USP6), questioning its functional effects in the cancer context." (PMID 35406420, 2022). "WNT2, MSH6, RAF, and Cyclin D1 (CCND1), genes involved in cancer processes, were also differentially expressed after exposure to 10 μM and 30 μM DON." (PMID 34440667, 2021). "MSH3, MSH6, APC and PIK3CA genes seem to play a bigger role in the path to cancer in this population." (PMID 28002797, 2017). "Of them, two driver genes, MSH6 and RUNX1T1, drew our attention, as they have been repeatedly reported to be involved in multiple cancer types." (PMID 29046615, 2017).
cancer (continued). "Further analysis revealed a deleterious missense mutation affecting the MutS domain III (T767I) of mutS homolog 6 (MSH6), a gene involved in the DNA MMR mechanism, which was shown to lead to hypermutated cancers." (PMID 28153049, 2017). "reliably assessed pan-cancer microsatellite instability using MSK-IMPACT assay and found that MSIsensor may be sensitive for the MSH6-equivocal EC, suggesting that MSIsensor performs well in MSH6-deficienct tumors." (PMID 40469174, 2025). "Because of sex-limited inheritance many path_MSH6 families did not fulfil these clinical criteria which assumed high cancer incidences in both sexes." (PMID 37821984, 2023).
cancer (continued). "Considering the high incidence of cancers arising in the digestive system and the frequency of 1.4% of MLH1-/PMS2-/MSH6- cases across the included entities, a considerable number of patients could fall into this subgroup overall." (PMID 36387226, 2022). "Conversely, preoperative chemotherapy or chemoradiation therapy can be associated with a reduced MSH6 protein expression in the absence of a germline or somatic MSH6 mutation in MSS CRC, leading to the overestimation of dMMR cancers and LS cases." (PMID 33530449, 2021). "Removing part of the colon or rectum in the absence of cancer or endoscopically non‐removable polyps is not generally recommended for path_MSH6 and path_PMS2 carriers." (PMID 34043773, 2021). "Next to MSH6 and MUTYH, CUX1 has been described as a cancer‐driving gene." (PMID 32615015, 2020). "We chose these cell lines based on the following rationale: HT-1080 is a NAPRTase-deficient cell line that requires NAMPT for NAD+ production, and DLD-1 is a MutS homolog 6 (MSH6)-lacking carcinoma cell line that can easily develop drug resistance." (PMID 31123329, 2019). "Importantly, MSH6, PTGS2, HDAC1, JUN, SLC2A1, and MMP1 were enriched in the pathway in cancer, of which MSH6 and MMP1 were candidate genes." (PMID 27034707, 2016).
cancer (continued). "Mutations in the MSI target genes IGF2R and BAX were found in one (33.3%) and two (66.7%) out of the three rectal MSI-H carcinomas, respectively, whereas no mutations were detected in TGFBR2, MSH3, and MSH6 microsatellite sequences in this test series." (PMID 20979647, 2010). "We describe six previously unreported MSH6 genetic alterations in 38 early-onset CRC patients with negative family history of HNPCC-related cancer." (PMID 16940983, 2006). "High-frequency microsatellite instability was found in the patient with the MSH6 deletion, but not in the other 27 carcinomas analysed." (PMID 16940983, 2006). "However, there were no cancer diagnoses in carriers of MSH6 c.3226C>T related to the compound heterozygous CMMRD patients." (PMID 38789506, 2024). "Additionally, we assessed the allele frequencies of the genes in the gnomAD non-cancer cohort (n = 134 187), which showed significant differences in BRCA1, BRCA2, CHEK2, MUTYH, MSH6, POLE, and ERCC3 genes in comparison to our non-HBOC groups." (PMID 39148954, 2024). "Four CRs (TRRAP, EP300, NSD2 and MSH6) having synthetic lethal interactions with MAP2 were integrated as a MAP2 CSL module in COAD, where MAP2 was affected by two taxnes (Paclitaxel and Docetaxel).These four CRs play roles in cell cycle, notch signaling pathway and mismatch repair in human cancers." (PMID 36180906, 2022). "However, all our patients with MLH1-/PMS2-/MSH6- cancers were over 60 years of age at time of diagnosis and did not have a familiar history suspicious for cancer predisposing syndromes." (PMID 36387226, 2022). "Two of these cancers were negative for MLH1/PMS2 and one showed isolated protein loss of MSH6." (PMID 32144630, 2020).
cancer (continued). "Molecular genetic testing using OncoKids Cancer Pane revealed no established variants of clinical significance, but some variants of unknown significance including APC, KMT2D, and MSH6 were found." (PMID 31702654, 2019). "While molecular genetic testing (OncoKids Cancer Panel) showed no established variants of clinical significance, it detected variants of unknown significance detected in APC, KMT2D, and MSH6." (PMID 31702654, 2019). "Similarly to cancer tissues, in adjacent mucosal tissues, MLH3 correlated with PMS1 and PMS2 (R = 0.887 and R = 0.931, P < 0.000, respectively), but, additionally, MLH3 also correlated with MSH6 (R = 0.857, P < 0.0001)." (PMID 24484585, 2014). "As shown, for male path_MLH1 and path_MSH6 carriers, mortality was similar after CRC compared to mortality after non-CRC cancers." (PMID 37181409, 2023). "No cancers were diagnosed in the MLH1 carriers, MLH1 non-carrier controls, or MSH6 non-carrier controls." (PMID 34678156, 2021). "Twenty‐two rare variants were shared by the three patients, including variants in the MSH6 (NM_000179.2: c.3299C > T, p.Thr1100Met) and MUTYH (NM_001128425.1: c.536A > G, p.Tyr179Cys) genes, while the other 20 genes could not be clearly linked to cancer predisposition." (PMID 32615015, 2020). "Our finding that MSH6 was expressed in all MSI-L and MSS cancers suggests that it is unlikely to play a significant role in this group." (PMID 16106253, 2005). "MSH6 and PMS2 carriers developed no cancers before 40 years of age." (PMID 27606285, 2016).